TIMP1 (TIMP metallopeptidase inhibitor 1)
Diseases named in the same sentence as TIMP1 in open-access papers (continued):
Sharing a sentence is not in itself a finding about the gene and the disease.
fibrosarcoma (13 papers, 2004 to 2024). A malignant mesenchymal fibroblastic neoplasm affecting the soft tissue and bone. "We showed that the TIMP-1 gene-deficient fibrosarcoma cells were considerably more sensitive to the chemotherapeutic drugs tested, compared to the corresponding TIMP-1 wild-type cells, confirming that TIMP-1 protects against chemotherapy in our model system." (PMID 17047657, 2006). "Also it has been shown that TIMP-1 deficiency increases sensitivity to chemotherapy induced apoptosis in fibrosarcoma cells." (PMID 26366732, 2015). "Therefore, we have established fibrosarcoma cells lines simultaneously deficient of the TIMP-1 and the PAI-1 genes, which can be used to investigate possible common characteristics of these two inhibitors (currently under investigation)." (PMID 17047657, 2006). "In vitro experiments on fibrosarcoma confirmed that intrathecal injection of the MMP inhibitor TIMP-1-GPI inhibited cell proliferation and migration, increased apoptosis, and enhanced sensitivity to chemotherapeutic agents." (PMID 39600645, 2024). "Intratumoral injections of TIMP-1-GPI into fibrosarcoma-bearing mice led to a significant decrease in the tumour mass." (PMID 29262667, 2017). "In order to investigate this hypothesis, we have established TIMP-1 gene deficient and TIMP-1 wild-type fibrosarcoma cell lines from lung tissue originating from littermate mice." (PMID 17047657, 2006). "In order to investigate this hypothesis, we have established TIMP-1 gene-deficient and TIMP-1 wild-type fibrosarcoma cells from mouse lung tissue." (PMID 17047657, 2006). "In an attempt to obtain a system, which can be used for further investigations of the protective function of TIMP-1 against chemotherapy-induced apoptosis, we have established TIMP-1 wild-type and TIMP-1 gene-deficient fibrosarcoma cell lines from lung tissue originating from littermate mice." (PMID 17047657, 2006). "Therefore, patients with fibrosarcoma may respond differently to TIMP-1-GPI treatment." (PMID 29262667, 2017). "In response to irradiation both TIMP-1 and TIMP-2 protein levels were increased in cell lysates and to a higher extent in CM derived from irradiated fibrosarcoma cells when compared to cell lysates and CM derived from control cells." (PMID 23631818, 2013). "Next, we assessed protein levels of TIMP-1 and TIMP-2 in cell lysates and CM derived from the HT1080 fibrosarcoma cells, which were treated with IR and patupilone." (PMID 23631818, 2013). "Moreover, in TPA-induced HT-1080 fibrosarcoma cells, XN suppressed both the activation and expression of MMP-9 and MMP-2, reduced the MT1MMP mRNA level, and induced a substantial TIMP-1 and TIMP-2 depletion." (PMID 34204745, 2021). "mRNA expression of TIMPs in matrix embedded fibrosarcoma cells demonstrates that cell-density significantly increased TIMP3 and TIMP4 expression but did not impact TIMP1 or TIMP2." (PMID 30220965, 2018).
inflammatory bowel disease (13 papers, 2008 to 2025). A spectrum of small and large bowel inflammatory diseases of unknown etiology. "Based on previous results from our group we further chose to quantify MMPs and TIMP-1 which are key enzymes in the matrix turnover and tissue destruction in inflammatory bowel diseases and also indicate pathogenic relevance during mycobacterial infections." (PMID 24728142, 2014). "TIMP-1 acts to down-regulate the profibrotic response and is associated with the degree of inflammation in the mucosa of patients with chronic inflammatory states (such as inflammatory bowel disease)." (PMID 25289758, 2014). "It was reported that CCR2+ monocytes promote colon fibrosis by inhibiting collagen degradation through tissue inhibitor of metalloproteinase (TIMP-1) production in inflammatory bowel disease (IBD)." (PMID 32626718, 2020). "Since chronic inflammation is associated with tissue remodeling in inflammatory bowel disease (IBD), we evaluated serum TIMP-1 and TIMP-4 levels in IBD patients, in comparison with healthy controls (HC)." (PMID 19036126, 2008). "Previous research on celiac disease and inflammatory bowel disease had reported similar imbalances, with elevated MMP-1 and MMP-2 and decreased TIMP-1 and -2 levels in the gut." (PMID 40524059, 2025).
influenza (13 papers, 2008 to 2024). An acute viral infection of the respiratory tract, occurring in isolated cases, in epidemics, or in pandemics; it is caused by serologically different strains of viruses (influenzaviruses) designated A, B, and C, has a 3-day incubation period, and usually lasts for 3 to 10 days. "Timp‐1‐deficient mice also showed fewer immune cell infiltrates and lung inflammation after influenza infection." (PMID 39267201, 2024). "In preclinical studies, Timp‐1 deficient mice exhibited less body weight loss than WT mice after Pseudomonas aeruginosa or influenza infection." (PMID 39267201, 2024). "Consistently, Timp-1-deficient mice experienced significantly less weight loss compared to wild-type mice after influenza infection." (PMID 36482481, 2022). "The level of MMP-9 and MMP-9 to TIMP-1 ratio in blood serum was increased in children with influenza caused encephalopathy, both in the group with worse prognosis and in the group who developed febrile seizures." (PMID 28104930, 2016). "In contrast, smoke exposure reduced the influenza-associated rise in lung TIMP-1 mRNA at d3." (PMID 18627612, 2008). "In preclinical studies, both influenza infection and LPS treatment can significantly induce the expression of TIMP-1 in the murine lungs, suggesting that TIMP-1 participates in the pathogenesis of ALI." (PMID 36482481, 2022). "The Timp1 expression levels were found to have excellent potential as predictors of BALF IgA production in nasal influenza vaccine." (PMID 33013912, 2020). "TIMP-1 protein was elevated in BALF of influenza infected mice at d3, more so if mice were smoke exposed prior to influenza infection." (PMID 18627612, 2008). "The apparent reduction in net gelatinase activity in BALF of smoke and influenza mice at d3, in comparison to influenza alone mice, is probably due to increased TIMP-1 activity." (PMID 18627612, 2008). "Protease activity is regulated at multiple levels, including transcription and post-translational cleavage, so it was interesting that prior smoke exposure altered transcriptional induction of proteases and TIMP-1 after influenza infection." (PMID 18627612, 2008). "Additionally, other research has demonstrated that increased TIMP1 expression promotes an immune response, has a pro-inflammatory effect in the lungs after influenza infection and facilitates an injurious phenotype." (PMID 32969837, 2020). "Even though the level of MMP-9 in these patients was comparable to the level of MMP-9 in patients with uncomplicated influenza, the patients with neurological complications had increased MMP-9 to TIMP-1 ratio in comparison to the patients without complications." (PMID 28104930, 2016).
keloid (13 papers, 2016 to 2024). An irregularly shaped, elevated mark on the skin caused by deposits of excessive amounts of collagen during wound healing. "The putative protein biomarkers identified in this study (i.e., IL-10, TIMP-1, and fibronectin) have been shown to exhibit diagnostic properties in fully developed HTSs or keloids in humans." (PMID 29458433, 2018). "Reduced PAI-1 and TIMP-1 gene expression may well show that ADSC-CM can reduce ECM deposition by keloids by regulating collagen degradation and associated gene expression." (PMID 29467010, 2018). "For instance, siRNA targeting TIMP-1/-2 has been observed to degrade collagen type I in keloid fibroblasts, while siRNA knockdown of heat shock protein 70 has resulted in significantly reduced collagen production." (PMID 39201463, 2024). "Instead of targeting the TGF-β signaling pathway directly, targeting its downstream target genes such as CTGF, PAI-1, and TIMP-1 would be a good alternative for keloid treatment." (PMID 38279232, 2024). "On the other hand, MMP-1, MMP-2, and TIMP1 were significantly upregulated in keloid fibroblasts by CM." (PMID 35083233, 2021). "Studies show that small interfering (si)RNA knockdown of TIMP1 in keloid fibroblasts leads to degradation of COL1." (PMID 29467010, 2018). "In our study, we found that TIMP1 decreases significantly in keloids after coculture with human ADSC-CM." (PMID 29467010, 2018). "Preliminary experiments revealed that TIMP1 may result in deposition of COL1 in keloids." (PMID 29467010, 2018). "In keloids, levels of MMP-1, MMP-2, MMP-13, TIMP-1, and TIMP-2 are increased, while MMP-3 levels are reduced compared to normal scars." (PMID 39201463, 2024). "Here, we observed that sorafenib not only reduced the expression of fibrotic ECM components but also modulated the MMPs/TIMP-1 ratio to potentially promote the degradation of ECM proteins, thereby promising a reverse of the established fibrosis in keloids." (PMID 27339758, 2016). "To further explore the impact of EP on the expression of ECM-degrading enzymes in keloids, we assessed the mRNA expression levels of metalloproteinase I (MMP1), metalloproteinase III (MMP3), and tissue inhibitor of metalloproteinases I (TIMP1) in both TGF-β1-treated HDFs and KFs." (PMID 38892032, 2024).
systemic sclerosis (13 papers, 2012 to 2025). A chronic disorder, possibly autoimmune, marked by excessive production of collagen which results in hardening and thickening of body tissues. "In both Crohn’s disease and systemic sclerosis, TIMP1 has been implicated in mediating excessive fibrosis." (PMID 23555662, 2013). "A previous report has additionally found an association between TGFβ2, TGFβ3, and TIMP1 in systemic sclerosis, which may ultimately be due to the contribution of IGF-II, based on the results of this study." (PMID 31765403, 2019). "Elevated serum levels of PIIINP, HA or TIMP-1 were found to be increased in other diseases, such as in patients with systemic sclerosis (SSc)." (PMID 36523781, 2022). "It is known that the expression of MMP-1 and TIMP-1 (MMP-1 inhibitor) reduces during the systemic sclerosis progression." (PMID 34258301, 2021). "In tears, however, we observed significantly higher levels of MMP-2/TIMP-1, -2 which indicates an imbalance in the MMP/TIMP system towards an increased breakdown of matrix proteins in the visual organ during systemic scleroderma." (PMID 33218057, 2020). "Knocking down CCN2 using siRNA reduced expression of pro-fibrotic markers (fibronectin p < 0.01, collagen type I p < 0.05, α-SMA p < 0.0001, TIMP-1 p < 0.05 and IL-6 p < 0.05) in TGF-β-treated lung fibroblasts derived from systemic sclerosis patients." (PMID 33662577, 2021). "However, systemic sclerosis fibroblasts did highly upregulate expression of POSTN, TNC, and TIMP1." (PMID 39989459, 2025).
adenoma (12 papers, 1995 to 2025). A neoplasm arising from the epithelium. "Furthermore, senescence-associated ECM remodeling genes (MMP1, 9, and 10 and TIMP1 and 2) exhibited increased levels in adenomas in relation to their matched malignant tissues where MMP10 was high in most of the samples." (PMID 40699620, 2025). "RT-qPCR displayed that the mRNA expression level of hub genes was higher in the adenoma than in normal mucosa except TIMP1." (PMID 36631756, 2023). "In our study, we found that TIMP1 presented a sequentially ascending trend through the normal colorectal mucosa–adenoma–carcinoma sequence, and the upregulation of TIMP1 indicated a poor survival prognosis, consistent with previous studies." (PMID 29659199, 2018). "Our results are in agreement to the findings of Mroczko et al20 who revealed that serum concentrations of MMP-9 and TIMP-1 were significantly higher in adenoma patients compared to control group, but lower than in patients with CRC." (PMID 29201696, 2015). "At a cutoff point yielding 97.7% specificity, sensitivities for detection of advanced adenoma were 21.3% and 21.9% by combining TIMP-1 or all three blood markers with iFOBT, respectively, compared with 19.7% for a model based on iFOBT alone." (PMID 22454079, 2012). "Taken together, our results showed that blood levels of sCD26, CRP and TIMP-1 were different in CRC patients compared with participants free of neoplasms, and TIMP-1 levels were also elevated in advanced adenoma patients." (PMID 22454079, 2012). "The TIMP-1 levels were found to be elevated in both advanced adenoma and CRC patients compared with neoplasm-free participants (P=0.005 for each comparison)." (PMID 22454079, 2012). "The expression of MMP-9 and TIMP-1 in the normal mucosa-adenoma-dysplasia-adenocarcinoma sequence of the colon was studied by few authors." (PMID 23202950, 2012). "For advanced adenoma, the model fit was significantly improved only by adding TIMP-1 or all three blood tests (P=0.002 and P=0.0007, respectively) according to likelihood ratio tests." (PMID 22454079, 2012). "The analysis of colonic adenomatous nodes revealed low expression of all the explored acute colitis-associated key genes: the expression levels of C3, Tyrobp, Mmp3, Mmp9, and Timp1 in adenoma tissue were 26.3, 3.4, 20.8, 11.9, and 27.7 times lower than those in the samples with acute colitis." (PMID 36901742, 2023). "Concentrations of TIMP-1 were also significantly elevated in advanced adenoma patients." (PMID 22454079, 2012). "For detection of advanced adenoma, TIMP-1 and sCD26 levels have been analysed previously." (PMID 22454079, 2012). "Among the seven upregulated genes the expression levels of which were over five times higher than those in the matched normal tissues, the expression levels of IGF-2, E1AF, iNOS, nm23, Smad4, and TIMP-1 genes were significantly higher in the early invasive carcinoma group than in the adenoma group." (PMID 15785755, 2005). "Correspondingly, patients with invasive adenomas had elevated serum MMP‐8 levels and lower TIMP‐1 levels, suggesting that these molecules serve as valuable markers for assessing IPA invasion." (PMID 39688352, 2024). "Interestingly, despite the proven association with CAC, TIMP1, MMP7, and ADAM8 were activated in IBD-affected colon tissues, which is fully in line with our data: the high expression of these genes was demonstrated in DSS-inflamed and adjacent to adenomas colon tissues in mice." (PMID 36901742, 2023). "TIMP1 expression did not significantly differ between adenomas and adenocarcinomas at the bulk level, or in the pairwise comparison." (PMID 40699620, 2025). "The blood levels of CRP, sCD26 and TIMP-1 showed statistically significant differences between CRC patients and neoplasm-free participants, and levels of TIMP-1 were furthermore significantly elevated in advanced adenoma patients." (PMID 22454079, 2012).
adenoma (continued). "Both MMP-9 and TIMP-1 mRNA were observed in all ten liver metastases but were absent in three adenomas and in all normal colonic mucosa and liver." (PMID 7669564, 1995). "No significant gene expression alterations could be detected in the stromal cells isolated from adenomas compared to the normals, but COL1A2, FADS1, MAL, PRIMA1, SULF1, THBS2, TIMP1 genes’ transcripts showed significant differences (p < 0.05) in logFc values for the tumour versus normal comparison." (PMID 26482433, 2015).
dementia (12 papers, 2010 to 2025). Loss of intellectual abilities interfering with an individual's social and occupational functions. "Our study highlights MMP-9 and TIMP-1 as potential biomarkers with moderate diagnostic accuracy for distinguishing dementia due to AD from cognitively unimpaired individuals." (PMID 38891891, 2024). "In our study, ROC curve analysis indicated that MMP-9 and TIMP-1 displayed moderate diagnostic accuracy in discerning dementia due to AD from CU subjects, according to the Swets criterion." (PMID 38891891, 2024). "This study investigated the diagnostic accuracy of plasma biomarkers—specifically, matrix metalloproteinase (MMP-9), tissue inhibitor of metalloproteinase (TIMP-1), CD147, and the MMP-/TIMP-1 ratio in patients with Alzheimer’s disease (AD) dementia." (PMID 38891891, 2024). "Several proteins, among them Insulin-like Growth Factor-1 (IGF-1), Metalloproteinase type 1 (TIMP-1), and Vascular Cell Adhesion Molecule type 1 (VCAM-1) were reported to mediate association between dementia and depression." (PMID 35326481, 2022). "Increased TIMP‐1 and MMP‐9 levels may disrupt the microvascular basal layer and lead to leukoaraiosis, which in turn causes cognitive impairment and dementia." (PMID 32431079, 2020). "Furthermore, the simultaneous investigation of MMP9, MMP2, and TIMP1 in CSF might provide the potential to distinguish between different types of dementia." (PMID 35454094, 2022). "In addition, TIMP‐1 concentrations were found to be related to left ventricular hypertrophy (LVH) and systolic dysfunctions, while LVH was independently associated with cognitive decline or dementia." (PMID 32431079, 2020). "For example, elevated levels of MMP-2, MMP-3, MMP-10, TIMP-1, and TIMP-2 were detected in the CSF of patients with delirium who had pre-existing dementia." (PMID 40507855, 2025). "MMPs and TIMPs have been also investigated as potential markers for dementia, resulting with the identification of altered plasma levels of MMP-9 and TIMP-1 in Alzheimer's Disease and vascular dementia, respectively." (PMID 20161799, 2010). "Conversely, MMP-2, MMP-12, and TIMP-1 were higher in acute trauma (e.g., hip fracture) compared with healthy controls or patients without dementia." (PMID 40507855, 2025).
Hyperglycemia (12 papers, 2016 to 2025). An increased concentration of glucose in the blood. "Db/db mice with pressure ulcers showed an impairment in the molecular regulation of hypoxia-related genes (Hif1a, Flt1, and Kdr), while extracellular matrix encoding genes (Itgb3, Timp1, Fn1, Col4a1) were upregulated by hyperglycemia and lesions." (PMID 35386010, 2022). "Here, we also found that reductions in the paracrine levels of TGF-β1, and Timp1 from SCs during hyperglycemia resulted in weakened fibroblast function." (PMID 36620211, 2022). "An experimental murine model was carried out, with the aim of studying the renal expression of Mmp10 and Timp1 during hyperglycaemia." (PMID 31913319, 2020). "Hyperglycemia causes an increase in TGF-β1 and TIMP-1 secretion." (PMID 35345832, 2022). "Homocysteine supplementation exacerbated hyperglycaemia-induced MMP-9 and ROS levels and decreased Timp1 and its interactions with MMP-9." (PMID 32150828, 2020). "In vitro, hyperglycemia impaired RSC 96 cell de-differentiation, cell-cycle re-entry, and cell migration, as well as their paracrine effects on myofibroblast formation, including the secretion of TGF-β and Timp1." (PMID 36620211, 2022).